CTLA4 (cytotoxic T-lymphocyte associated protein 4)
Diseases named in the same sentence as CTLA4 in open-access papers (continued):
Sharing a sentence is not in itself a finding about the gene and the disease.
Graves disease (continued). "Considering that allelic variants of CTLA-4 are involved in Graves’ disease development, CTLA-4 and PD-1 gene polymorphisms might be involved in the occurrence of TED." (PMID 36204105, 2022). "Furthermore, the CTLA4 gene has a critical immunomodulatory function in maintaining peripheral self-tolerance, and the CTLA4 gene variants +49 A/G and CT 60 A/G were found to be associated with Graves' disease in a Kashmiri population." (PMID 34567510, 2021). "A recent study suggested that HLA and CTLA4 polymorphisms might confer a synergistic risk in the susceptibility to Grave’s disease in humans." (PMID 26401336, 2015). "Similarly, patients with vitiligo and at least one other autoimmune condition, including either Graves' disease or Hashimoto's thyroiditis, have been found to have a cytotoxic T lymphocyte antigen-4 (CTLA-4) polymorphism, which is involved in T cell apoptosis." (PMID 22099887, 2011). "Therefore it is plausible to hypothesize that blocking CTLA-4 results in the development of activating antibodies against the TSH receptor thereby causing Graves' disease in susceptible individuals." (PMID 26881150, 2016). "The aim of this study was to systematically evaluate the correlation between the rs231775 locus polymorphism in the cytotoxic T lymphocyte-associated antigen 4 (CTLA-4) gene and genetic susceptibility to Graves’ disease (GD) in children." (PMID 37128592, 2023). "Among these, PTPN22, CTLA4, HLA_DRB1, FCRL3, and IL2RA are common susceptibility genes between both conditions, while CD40 is exclusively associated with Graves’ disease and RA." (PMID 38093966, 2023). "A comprehensive study mapping the gene cluster found that variations in the CTLA4 30 area impact autoimmune responses in Graves' disease and Hashimoto’s thyroiditis." (PMID 35911325, 2022). "CTLA-4 seems to have a role in the development of Graves’ disease and immune dysregulation syndrome, through autosomal dominant mutations." (PMID 36204105, 2022). "Of note, in our review, all 6 patients with Graves’ disease were treated with anti-CTLA-4 mAb (5 as monotherapy)." (PMID 30693099, 2019). "This study was designed to explore the association between Graves disease (GD) and thyroid-stimulating hormone receptor (TSHR) and cytotoxic T-lymphocyte-associated antigen 4 (CTLA-4) single nucleotide polymorphisms (SNPs)." (PMID 31565653, 2019). "Single-nucleotide polymorphism (SNP) haplotype and SNP-SNP interactions of CTLA-4 and CD40 genes, with susceptibility to Graves’ disease (GD), were explored in a Chinese Han population." (PMID 30223781, 2018). "Thyroiditis is the most frequent cause of thyrotoxicosis and is seen more commonly with anti-PD1/PD-L1 drugs than with anti-CTLA-4 agents; Graves’ disease is very rare and occurs more commonly with anti-CTLA-4 drugs." (PMID 29162153, 2017). "The meta-analysis study shows consistent associations of Graves’ disease and Hashimoto thyroiditis with CT60 and clarifies the important role of the CTLA4 locus in determining the risk of autoimmune thyroid diseases." (PMID 26963610, 2016). "Frequency of haplotypes of the CTLA4 gene in adult Graves disease, pediatric Graves disease, Hashimoto disease patients and controls." (PMID 27111218, 2016). "In addition, ICIs-related Graves’ disease has been reported in patients treated with the CTLA-4 blocker ipilimumab." (PMID 33806774, 2021). "There are several points that support this relation between CTLA-4 and Graves' disease." (PMID 26881150, 2016). "Furthermore in the same study there was a relationship between allelic variation of the CTLA-4 gene and circulating free T4 concentration at the time of diagnosis suggesting a link between the gene and the severity of Graves' disease." (PMID 26881150, 2016). "The fact that anti-CTLA-4 treatment provokes Graves’ disease might revive this hypothesis." (PMID 36811715, 2023).
Graves disease (continued). "Furthermore, several SNPs, such as A49G, CT60, JO31 in the CTLA-4 gene, rather than in CD28 gene have been revealed association with Graves' disease." (PMID 20352109, 2010).
autoimmune thyroid disease (52 papers, 2005 to 2025). Inflammatory disease of the thyroid gland due to autoimmune responses leading to lymphocytic infiltration of the gland. "It has been demonstrated that a polymorphism of the cytotoxic T lymphocyte antigen-4 (CTLA-4) gene is linked to autoimmune thyroiditis as well as to granulomatosis with polyangiitis." (PMID 38914775, 2024). "It has been shown that the blockade of cytotoxic T lymphocyte-associated protein 4 (CTLA-4) exacerbated autoimmune thyroiditis in NOD-H2h4 mice and induced an expression of IDO1 in mouse thyroid glands and peripheral antigen-presenting cells." (PMID 38514790, 2024). "Single nucleotide polymorphisms (SNPs) involving the CTLA‐4 gene have been implicated in several autoimmune disorders such as Type 1 diabetes, autoimmune thyroid disease, autoimmune hepatitis, and primary biliary cirrhosis." (PMID 35071782, 2022). "Cytotoxic T-lymphocyte associated protein 4 (CTLA-4) inhibition worsened autoimmune thyroiditis in mice via the production of interleukin (IL)-2, interferon gamma, IL-10, and IL-13 cytokines." (PMID 34234669, 2021). "Hyperthyroidism is usually found as a transient symptom at the beginning of autoimmune thyroiditis or associated with Graves’ disease after anti-CTLA-4 treatment." (PMID 32500465, 2020). "It was demonstrated that 49A/G and CT60 polymorphisms of CTLA-4 gene display strong causal relationship with autoimmune thyroid diseases (AITD) in Slovenian population." (PMID 23072316, 2012). "The observed link between AQP4-IgG-negative status and thyroid autoimmunity suggests that overlapping autoimmune risk alleles (e.g., CTLA-4 polymorphisms) or environmental triggers (e.g., iodine exposure) may influence self-reactivity." (PMID 40933045, 2025). "Furthermore, using a NOD.H-2h4 model to assess anti-CTLA-4-associated autoimmune thyroiditis, systemic administration of anti-CTLA-4 induced high titers of anti-thyroglobulin antibodies while hydrogel-based administration did not." (PMID 35621582, 2022). "It remains uncertain whether the correlation of polymorphisms in CTLA-4 and, less often, in PDL-1 genes with susceptibility to thyroid autoimmunity translates into the association of a CTLA-4 and PDL-1 blockade with ir thyroid disorders." (PMID 34771441, 2021). "Besides similar HLA haplotypes, association with the gene encoding cytotoxic T-lymphocyte-associated antigen-4 (CTLA-4), a candidate gene for conferring susceptibility to thyroid autoimmunity, also has been reported." (PMID 25788942, 2015). "Additionally, CTLA-4 mutations enhance susceptibility to autoimmune thyroid and skin disorders." (PMID 39337081, 2024). "Joint susceptibility genes identified for T1DM and autoimmune thyroid diseases, including hypo- or hyperthyroidism, are HLA class II genes, PTPN22, CTLA-4 and FOXP3." (PMID 38116309, 2023). "CD and AITD have also been equated outside the HLA region to the gene encoding cytotoxic T-lymphocyte-associated antigen-4 (CTLA-4), a potential gene for thyroid autoimmunity susceptibility." (PMID 35911325, 2022). "A soluble form of CTLA‐4 (sCTLA‐4) has also been shown to be increased in systemic lupus erythematosus, myasthenia gravis, and autoimmune thyroid disease." (PMID 35071782, 2022). "The patients who develop autoimmune thyroiditis after CTLA-4 blockade therapy exhibit symptoms such as pain, hand tremor, periorbital swelling, or tachycardia." (PMID 32500465, 2020). "The CT60 in the 3’UTR region of CTLA4 gene is also the most promising locus for the autoimmune thyroid diseases." (PMID 26963610, 2016). "The association of the cytotoxic T lymphocyte-associated antigen 4 (CTLA-4) gene and susceptibility to autoimmune thyroid diseases (AITDs) has been studied extensively." (PMID 25878663, 2015). "At present, the CTLA-4 (chromosome 2q33), thyroglobulin (or ZFAT) (8q24) and likely HLA genes (6p21.3) are the only susceptibility loci for HT and thyroid autoimmunity to be mapped." (PMID 15762980, 2005).
autoimmune thyroid disease (continued). "Another such molecule, CTLA‐4, which has been implicated in the pathogenesis of autoimmune thyroiditis, appeared to play no role in CSU." (PMID 40635160, 2025). "It more commonly develops in cases showing previous positivity of antithyroid antibodies and a family history of autoimmune thyroid disease and in patients treated with programmed death 1 (PD1) inhibitors than cytotoxic T-lymphocyte-associated protein 4 inhibitors." (PMID 39498471, 2024). "In addition, the gene encoding cytotoxic T-lymphocyte-associated antigen-4 (CTLA-4) is associated with CD and autoimmune thyroid disease." (PMID 28030626, 2016). "The crucial role of CTLA-4 in maintaining self-tolerance breakdown of which leads to the initiatition of a primary autoimmune response has been demonstrated in several murine models of autoimmune diabetes and autoimmune thyroiditis." (PMID 15762980, 2005). "Association of CTLA-4 with the production of thyroid antibodies, an event that often represents the subclinical stage of AITD, can explain non-specific mechanism of CTLA-4-mediated susceptibility to the development of thyroid autoimmunity." (PMID 15762980, 2005). "However, the phenotype in autoimmune thyroid diseases is not determined only by CTLA-4 polymorphisms." (PMID 37568880, 2023). "However, we did not detect variants in a number of well-known autoimmune thyroid disease genes (e.g., CTLA4, HLA class I and II)." (PMID 30367059, 2018). "It is worth noting that two patients with CTLA4 defects displayed no autoimmune manifestations, while the remaining three suffered from autoimmune thyroiditis, and one also suffered from pernicious anemia." (PMID 38792965, 2024). "No prior anti-PD-1 or anti-CTLA-4 therapy had been administered in this case, indicating a probable pre-existing thyroid autoimmunity." (PMID 38136348, 2023). "Family studies showed linkage between CTLA-4 and GD, thyroid antibody production and autoimmune thyroid disease but not specifically to HT, probably due to lack of their power." (PMID 15762980, 2005). "The genes responsible for autoimmune thyroid diseases could be categorized as either thyroid-specific types (e.g., thyroglobulin and TSH receptor) or immune-modulating types (e.g., Forkhead box P3 (FOXP3), CD25, CD40, CTLA-4, and HLA)." (PMID 29884162, 2018). "Thus, some authors suggest that some persons with the G/G genotype (rs 231775) in the CTLA-4 gene will not develop autoimmune thyroid diseases, while those with the A/A genotype may develop AITDs." (PMID 37568880, 2023).
breast tumor (51 papers, 2012 to 2026). "In our current communication, we analyzed the impact of dietary salt modification on therapeutic and systemic outcomes in breast-tumor-bearing mice following anti-cytotoxic T-lymphocyte-associated protein 4 (CTLA4) monoclonal antibody (mAb) based ICI therapy." (PMID 35741331, 2022). "Taken together, these results show differences in the kinetics of CD4 + and CD8 + T cell proliferation and trafficking in response to ICB treatment and suggest distinct underlying mechanisms to explain the impact of α-PD1 and α-CTLA4 treatment on immunologically “cold” breast tumors." (PMID 38918836, 2024). "However, various studies reported the association between the risk of breast tumors and CTLA-4 (−658 C/T) polymorphisms." (PMID 38186404, 2023). "We demonstrate that targeting CD73 in qM breast tumors sensitizes them to anti-CTLA4 ICB therapy in a CD4+ T cell-dependent manner." (PMID 42118667, 2026). "In a retrospective analysis of the prognostic value of 50 immune checkpoints in BC, Fang and colleagues found that CTLA4 gene expression was upregulated in breast tumors compared to normal breast tissue, with the highest expression found in TNBC45." (PMID 40523912, 2025). "We also noted a similar response in the 4T1-BALB/cJ murine breast tumor model following the combination of anti-TGFβ mAb with anti-CTLA4 mAb." (PMID 38891044, 2024). "In our murine breast tumor models, the combination of anti-TGFβ with anti-CTLA4 significantly reduced tumor progression over treatment with anti-CTLA4 alone." (PMID 38891044, 2024). "Although blocking these molecules, mainly CTLA-4, PD-1 and PD-L1, has emerged as a promising immunotherapeutic approach, patients with the most aggressive breast tumor subtypes still exhibit poor survival." (PMID 37152039, 2023). "CTLA-4 inhibitors avoid immune escape of breast tumor and achieve the goal of treatment by blocking the CTLA-4 pathway." (PMID 36765522, 2023). "IT LSAM-DTX injections into syngeneic murine breast tumors reduced TV and, in combination with anti-CTLA-4, further reduced primary tumor growth and extent of thoracic metastasis." (PMID 36058988, 2023). "It is also reported from other studies that overexpression of CTLA-4 is about over 50% of breast tumor tissues in comparison to that of the tissues of benign breasts." (PMID 38186404, 2023). "Firstly, we measured the expression levels of PD-L1 and CTLA-4 on breast tumor cells and immune cells subpopulations following activation with SEB." (PMID 36358708, 2022). "We also observed high expression of the immune checkpoint regulator CTLA-4 in breast tumor infiltrates from the exposed patients." (PMID 36358618, 2022). "We found that pharmacological inhibition of cPLA2 reduced breast tumor growth and metastasis with a decreased abundance of only CTLA4+ CD4+ T cells and M2-TAMs." (PMID 35135586, 2022). "In this study, a syngeneic breast tumor mouse model was used to investigate the effect of [177Lu]Lu-DOTA-folate as an immune stimulus to enhance anti-CTLA-4 immunotherapy." (PMID 33078260, 2021). "The concept of using external radiation to sensitize poorly immunogenic tumors and enable immune response to CTLA-4 blockade has been demonstrated previously in a 4T1 breast tumor model and in several other preclinical and clinical studies." (PMID 33078260, 2021). "We have shown that upregulation of PD-1, CTLA-4 and LAG-3 in breast tumor tissues is associated with low enrichment of repressive histones, H3K9me3 and H3K27me3, in their promoter regions." (PMID 32760400, 2020). "In accordance with our previous findings in breast tumors, the distribution of H3K9me3 was lower in colorectal TT of PD-1 and H3K27me3 was lower in TT of the CTLA-4 and TIM-3 promoter regions compared with NT." (PMID 30081950, 2018). "We investigated the expression of CTLA-4 and PD-L1 in human breast tumors and provided a scoring system for the systematic evaluation of CTLA-4 staining." (PMID 29672601, 2018).
breast tumor (continued). "Our findings in this study further support future investigations of anti-CTLA-4 immunotherapies in the CTLA-4-positive breast tumors which can be objectively assessed by the introduced scoring system." (PMID 29672601, 2018). "In contrast, fractionated RT was found to be more effective than single fraction RT in tumor control when combined with anti-CTLA4 antibody for a murine model of breast tumor." (PMID 22666458, 2012). "Importantly, targeting CD73 completely sensitizes quasi-mesenchymal (qM) breast tumors to anti-CTLA4 ICB therapy." (PMID 42118667, 2026). "Similarly, another study reported that anti-CTLA-4 mAB in combination with PI3Kα inhibitor provided synergistic antitumor activity, regressed breast tumors by 60%, and sensitized the tumor to ICI compared to ICI alone." (PMID 38956700, 2024). "applied metformin and anti-CTLA-4 antibody to a 4T1 breast tumor model in mice." (PMID 37860188, 2023). "The use of immune checkpoint blockade (ICB) using antibodies against programmed death receptor (PD)-1, PD ligand (PD-L)-1, and cytotoxic T-lymphocyte antigen 4 (CTLA-4) has redefined the therapeutic landscape in solid tumors, including skin, lung, bladder, liver, renal, and breast tumors." (PMID 34930377, 2021). "In addition, a cancer gene therapy using the IL36-loaded nanoparticles in combination with CTLA-4 mAbs additively reduced lung metastasis of breast tumor cells." (PMID 32351508, 2020). "Overall, CTLA-4 was over-expressed in 49 of 93 (52.7%) breast tumors." (PMID 29672601, 2018). "Thus, the significant reduction in the circulating levels of Tregs in women with LLABCs undergoing NAC was associated with a substantial and significant concomitant reduction of FOXP3+ and CTLA-4+T cells infiltrating the breast tumours." (PMID 27777963, 2016). "The most pronounced delays in tumor progression for both 4T1 and E0771 breast tumor models were observed when the treatment protocol combined ketotifen, sonopermeation, Doxil, and immune checkpoint inhibitors (ICIs), specifically anti-PD-1 and anti-CTLA-4 antibodies." (PMID 40837706, 2025). "Interestingly, breast tumor-bearing mice on anti-CTLA4 therapy when placed on a low-salt diet demonstrated decreased peripheral circulatory levels of inflammatory cytokines (IFNγ and IL-1β) and reduced lung infiltrating of inflammatory immune cells along with reduced tumor progression." (PMID 40563574, 2025). "Recently, single-cell analysis of human breast tumours identified a cluster of FAP+ fibroblasts whereby subpopulations enriched in ECM proteins and TGFβ1 signalling were linked with regulation of host immune response via upregulation of PD-1 and CTLA4 expression on Tregs." (PMID 34740105, 2021). "In addition, it was found that IL-2 significantly decreased the expression of the inhibitory receptor CTLA-4 and increased the expression of B lymphocyte-induced maturation protein-1(Blimp-1), leading to the activation of effector T cells and the induction apoptosis of the breast tumor cells." (PMID 42192107, 2026). "Our findings revealed that VISTA is highly expressed in the breast tumor microenvironment and is more correlated with PD-1 than PDL-1 or CTLA-4." (PMID 37152039, 2023). "Elevated expression of PD-1, CTLA-4, and TIM-3 genes in breast tumor tissues was found to be mediated by DNA hypomethylation in the CpG islands of their promoter regions." (PMID 32760400, 2020). "Immune inhibitory receptors (PD1, CTLA4, LAG3 and TIM3) were co-expressed on certain subtypes of T cells in breast tumors, and PD1 and CTLA4 were both positively correlated with CD8+ Tcm and CD8+ T cells." (PMID 32728493, 2020). "Initially, we found that immune checkpoints including PD-1, CTLA-4, TIM-3, and LAG-3 were upregulated in breast tumor tissues." (PMID 29983831, 2018). "Significantly higher levels of Tregs (FOXP3+, CTLA-4+) and CD56+ NK cells were documented in ALN metastases than in the corresponding primary breast tumours." (PMID 29390966, 2018).